CD4 (CD4 molecule)
Diseases named in the same sentence as CD4 in open-access papers (continued):
Sharing a sentence is not in itself a finding about the gene and the disease.
malaria (continued). "Given the essential role of T cells in malaria immunity, especially at the pre-erythrocytic stage, designing vaccines that effectively stimulate both CD8+ and CD4+ responses is a critical step toward enhancing protection and blocking transmission." (PMID 40791414, 2025). "When malaria follows established SIV infection, a remarkable increase in CD4+CD28highCD95high central memory T cells occurs, accompanied by enhanced SIV-specific T cell responses." (PMID 40950582, 2025). "Further studies are required to investigate the age-dependent induction of other regulatory cell responses during malaria, such as Tr1 CD4 T cells which co-produce IL10 with IFNγ and dominate the CD4 T cell compartment during malaria infection." (PMID 41027884, 2025). "Tests included CD4 cell counts, blood sugar, rapid tests (HIV, syphilis, hepatitis, malaria, pregnancy, urine TB LAM, CrAg), and near-POC molecular tests like GeneXpert for HIV early infant diagnosis and viral load." (PMID 41460810, 2025). "Then, using specimens from an observational study in a high malaria transmission area in Uganda (PRISM), we assessed the recognition of these candidates by CD4+ T cells from exposed children." (PMID 39993000, 2025). "CD4 counts showcased a positive correlation with red blood cell counts, hemoglobin concentrations, and hematocrit levels in HIV-malaria co-infected patients." (PMID 40950582, 2025). "Activation of CD4 and CD8 T cells has been correlated with protective immunity to malaria, and they can differentiate into several functionally distinct subsets in the presence of various cytokines." (PMID 39830896, 2024). "The expression of PD-1 on CD4+ and CD8+ T cells has been reported to provide modulatory signals during malaria, but its function in the modulation of γδT cells remains unresolved." (PMID 38265549, 2024). "Upon stimulation with P. falciparum–infected erythrocytes, CD4+, γδ, and EMRA CD8+ T cells produced IFN-γ and/or TNF, indicating their ability to mediate responses that eliminate malaria parasites." (PMID 38716733, 2024). "PD-1 and LAG-3 are highly expressed in CD4+ and CD8+ T cells, and the expansion of such cells among peripheral blood mononuclear cells in malaria-infected patients has been reported." (PMID 38265549, 2024). "Additionally, other mechanisms may include antigen-specific T cell clone deletion, as demonstrated in a mouse model of malaria, where adoptively transferred CD4+ T cells are deleted from the periphery and tissues in an IFN-γ-dependent manner following infection." (PMID 39132440, 2024). "Understanding the role of Tr1 cells, and TNFα expressing CD4+ T cells, in gravidity-dependent antimalarial protection may help efforts towards developing vaccines and other therapeutic interventions to protect pregnant women from the adverse outcomes of malaria in pregnancy." (PMID 37634385, 2023). "HIV infection is responsible for a gradual depletion of CD4+-T cells and expansion of CD8+-T cells, which play a key role in the immune response against the blood stages of malaria parasites." (PMID 36600836, 2023). "In a similar context, mice immunized with a Plasmodium yoelii circumsporozoite protein along with 7DW8-5 increased the percentage of central memory CD4+ T cells and effector memory CD8+ T cells, promoting malaria-specific immunity." (PMID 38136283, 2023). "Our results above indicate that STING-dependent IFN-β1 production by human CD4+ T cells drives Tr1 cell development in vitro and a similar STING-dependent pathway promotes Tr1 cell development in vivo in experimental malaria." (PMID 37781920, 2023). "We observed that CD4+ cells are lower and CD8+ cells are higher in PvVir14-IgG+ subjects compared to malaria-naïve healthy donors." (PMID 37027391, 2023). "Percentages of CD4+ T cells and CD45RO− memory like T cells have been shown to be higher in peripheral than placental blood in malaria exposed pregnant women." (PMID 37634385, 2023).
malaria (continued). "The ZEB2+ memory CD4+ T cells in these two groups expanded only in the blood of those gaining clinical immunity but not in the other group, consistent with our original hypothesis that expansion of these cells may correlate with the acquisition of protective immunity against clinical malaria." (PMID 38001069, 2023). "In WHO 2021, cotrimoxazole prophylaxis is recommended for PWH with a CD4 + count < 350 cells/mm3, clinical stage 3 or 4, or to any PWH in settings with high prevalence of malaria or severe bacterial infection." (PMID 37996881, 2023). "Since ZEB2+ memory CD4+ T cells contained clonally expanded P. falciparum CSP-specific T cells, we next hypothesized that protected patients should have greater proportion of these cells than susceptible ones, if these cells are indeed associated with clinical immunity against malaria." (PMID 38001069, 2023). "We have recently shown that blood-stage malaria in experimental models but also in human malaria is accompanied by an induction of co-inhibitory molecules like PD-1, LAG-3, and TIM-3 on CD4+ as well as CD8+ T cells." (PMID 35874786, 2022). "As expected, most participants circulating pro-inflammatory CD4+ T cells reacted to the stimulation with the vaccine antigen GMZ2 at baseline, most likely due to their lifelong natural exposure to malaria parasites." (PMID 35715803, 2022). "CD4+ and CD8+ T cells are considered to play a crucial role in protection against malaria parasites." (PMID 36380374, 2022). "Some studies have corroborated that CD4+ T cells, as the prime targets for reproduction by HIV-1, play a vital role in immune responses to malaria." (PMID 36104731, 2022). "Apart from the CD4+ T cell response, CD8+ T cells are vital in offering protection against liver-stage malaria." (PMID 35812841, 2022). "Once the adaptive immunity is established, CD4+ T cells become the major producer of IFN- γ which further activates cytotoxic T cells and performs a vital role in the cytotoxic killing of malaria parasite infected cells." (PMID 35277125, 2022). "Using one-way ANOVA and Dunnett’s Multiple Posthoc to determine difference between control and the three groups, there was significant decline in CD4+ T and CD8+ T cells count and within increase in severity of malaria densities (p<0.0001)." (PMID 35223394, 2021). "There was a significant decline in CD4+ T and CD8+ T cells counts with an increase in malaria densities (p<0.0001)." (PMID 35223394, 2021). "CD4+ and CD8+ T cell responses to this malaria antigen were also found to be heterogeneous within individuals across our study populations." (PMID 34771539, 2021). "This aligns with various studies on T cell response to malaria in children, where majority reported declined CD4+ and CD8+ T cell counts in malaria-infected children." (PMID 35223394, 2021). "IL-10 responses to EBV and malaria antigen were comparable for Kisumu and eBL children; however, Nandi children had significantly higher CD4+ and CD8+ T cell IL-10 responses to malaria (typically an acute infection in this study population) compared to EBNA1." (PMID 34771539, 2021). "Protection against malaria through RTS, S/AS01 vaccines is through the induction of high levels of both anti-CSP antibodies and CD4 T cells expressing IL-2, TNF, IFN- and the co-stimulatory marker CD40L." (PMID 32708179, 2020). "We found that the prevalence of both CD4+ and CD8+ T cells was decreased in mice during the progression of malaria disease." (PMID 33298881, 2020). "In this study, we identified a population of CD4+ T cells that expresses very high levels of CD4 and CD38 (CD4hiCD38hi) in adult malaria patients living in malaria‐endemic regions." (PMID 33282291, 2020). "Expression of high levels of PD-1 and LAG-3 on CD4+ and CD8+ T cells, and expansion of such cells among peripheral blood mononuclear cells (PBMCs) of malaria-infected patients has been reported." (PMID 33519801, 2020).
malaria (continued). "TIGIT expression in malaria patients was significantly increased on bulk CD8+ and CD4+ T cell populations." (PMID 32983106, 2020). "Accumulated findings indicated that TIM-3 was responsible for inhibiting T lymphocytes (CD4+ Th1/Th2, CD8+, and γδ T cells), NK cells, and macrophages responses to malaria treatment." (PMID 33363057, 2020). "We determined the expression of the immune checkpoint inhibitor PD-1 expressed on CD4+ and CD8+ T cells in malaria-infected mice." (PMID 33298881, 2020). "When immunocompromised mice that lack T cells were treated with Moringa, then infected with malaria, there was a significant growth in the parasites compared to control mice, confirming that Moringa can promote parasite growth, but in the presence of CD4+ T cells, the parasites may be controlled." (PMID 32033605, 2020). "In malaria we observed an upregulation of both PD1 and TIGIT on CD8+ and CD4+ T cells compared to healthy donors." (PMID 32983106, 2020). "It is well established that in addition to B cells, CD4+ and CD8+ T cells as well as IFN-γ play an important role in this mouse model for blood stage malaria." (PMID 31214184, 2019). "The first finding of this study showed that the CD4 and CD8 expression was high in the placenta of malaria infected mice." (PMID 32099563, 2019). "The study findings also showed significant stock-outs of malaria RDTs, HIV, CD4, HBV POC diagnostics kits at different study settings." (PMID 31340833, 2019). "We observed that CD4+ T cells expressing both CD57 and PD-1 were increased in children with symptomatic malaria compared to asymptomatic (p = 0.0127) and healthy controls (p = 0.0071)." (PMID 31316497, 2019). "In addition to isoniazid, across CD4 strata cotrimoxazole prophylaxis also reduces mortality and risk of serious bacterial infections and malaria within endemic regions and is recommended regardless of CD4 count in areas with a high prevalence of severe bacterial infections and/or malaria." (PMID 30645592, 2019). "In addition, recent data suggests that Th1 cell development may also influence the development of T follicular helper (Tfh) cells, another important CD4+ T cell subset in malaria needed for the expansion of antigen-specific B cell populations and the production anti-parasitic antibody." (PMID 30809232, 2019). "Evidence suggests that people with HIV have more frequent episodes of symptomatic malaria and that malaria increases HIV plasma viral load and decreases CD4+ T cells." (PMID 31337411, 2019). "Higher IFN-γ/IL-10+ specific-CD4+ T cell responses were observed amongst children heavily exposed to malaria compared to children with low exposure indicating that CD4+ T cells may play an important immunomodulatory role in the pathogenesis of childhood malaria." (PMID 30774635, 2019). "The consequences of malaria and HBV single infections result in low Hb, low CD4 count in the first trimester, low birth weight, fever, and urinary tract infection (UTI)." (PMID 30344800, 2018). "Taken together, our results depicted the importance of ICOS expressing CD4+ and CD8+ T cells in malaria parasite growth and lethality through IFN-γ production and T-bet expression." (PMID 29892278, 2018). "We found both CD4+ and CD8+ T cells expressed transcription factor, T-bet, which is already known to be involved in malaria pathogenesis." (PMID 29892278, 2018). "A significant increase in immune activation in the CD4 and CD8 T cells was observed in clinical malaria." (PMID 30005684, 2018). "The role of CD4+ and/or CD8+ T cells as well as IFN-γ as important effectors of immunity against the preerythrocytic stages was described in various murine malaria studies [reviewed in Ref." (PMID 29628927, 2018). "The phenotype of CSP-specific CD4+ T cells that has been associated with vaccine-induced protection against clinical episodes of malaria is TNF-α+, but not IL-2+ or IFN-γ+;56,79 and in part, TNF-α+ CD4+ T cells may also be induced by natural exposure to malaria parasites." (PMID 28934066, 2018).
malaria (continued). "Malaria/HIV coinfection has been shown to have the following effects: low Hb, low CD4 count in the first trimester, and low birth weight, fever, and urinary tract infection among others." (PMID 30344800, 2018). "In a prior study with adult malaria patients, we detected IFN-γ+/IL-10+ and IL-10-single positive CD4+ T cells which expressed co-inhibitory molecules in a T cell subset that exerted suppressor function in vitro." (PMID 29555909, 2018). "In conclusion, our data demonstrate that in the context of severe blood‐stage malaria, cDC1 promote the differentiation of parasite‐specific IFNγ+ TNF+ Th1 cells, to the expense of more regulatory IL‐10+ CD4 T cells." (PMID 28935714, 2017). "Nevertheless, the depletion of IFNγ-producing cells resulted in decreased RTS,S-mediated protection in a malaria challenge model, accompanied by a decreased CSP-specific CD4+ T-cell response and limited effects on protective antibodies." (PMID 29263880, 2017). "Incidence of malaria by ART regimen overall and stratified by treatment arm and current CD4+ stratum." (PMID 28121670, 2017). "This work profiles the P. berghei blood‐stage MHC II immunopeptidome, highlights the potency of cDC1 to present malaria antigens on MHC II, and reveals a major role for cDC1 in regulating malaria‐specific CD4 T‐cell responses." (PMID 28935714, 2017). "Malaria parasitic density ≥10,000 parasites/μl (AOR: 0.13; (95% CI: 0.03, 0.57) and CD4 + count ≤ 200 cells/μl (AOR: 4.77; 95% CI: 1.23, 18.45) were predictors of leucopenia." (PMID 28184306, 2017). "Since CD4+ T cells also play an important role in the control of blood-stage malaria, we determined the influence of CYLD on the CD4+ T cell numbers in the blood and brain during ECM." (PMID 28203236, 2017). "This interaction induces cytophilic antibodies as well as CD4+ and CD8+ T cell responses that protect mouse models from malaria parasites." (PMID 29312230, 2017). "Malaria parasitic density (AOR: 0.13; 95% CI: 0.03, 0.57) and CD4 + count (AOR: 4.77; 95% CI: 1.23, 18.45) were predictors of leucopenia." (PMID 28184306, 2017). "Furthermore, HIV in turn facilitates the rate of malaria transmission which in turn causes strong CD4 cell activation and up-regulation of pro-inflammatory and cytokines production which create an ideal microenvironment for the spread of HIV among CD4 cells for rapid HIV-1 replication." (PMID 28346490, 2017). "Decreased proportion of subjects with high levels of CD4+ and CD8+ T-cells was found especially in the group of patients with recurrent malaria." (PMID 27581163, 2016). "The unbalanced CD4+/CD8+ T-cells ratio, as well as increased IL-10 levels were correlated with the number of recurrent malaria episodes." (PMID 27581163, 2016). "CD4 T cells were compared in infants born to mothers with and without evidence of Plasmodium infection during pregnancy to test the hypothesis that in utero malaria exposure would result in an expansion of fetal regulatory CD4 T cells and/or effector CD4 T cells." (PMID 27717402, 2016). "The researchers enrolled 500 HIV-infected adults living in a malaria-endemic region of Kenya (an area where malaria is always present) who had been treated with ART for ≥18 months, who had a CD4 count of >350 cells/mm3, and who were taking CTX." (PMID 26731191, 2016). "Analyses of lymphocyte subsets showed significant decrease in the proportion of subjects with high levels of CD4+ T-cells (p = 0.036) and CD8+ T-cells (p = 0.0034), particularly in the group of patients with recurrent malaria." (PMID 27581163, 2016). "Tregs were modestly increased in infants exposed to malaria early in gestation, whereas activated CD127+ CD4 T cells of an effector-memory phenotype were expanded in infants with active placental infection at the time of delivery." (PMID 27717402, 2016).
malaria (continued). "Not only CD4+ T cells, but also more CD8+ T cells from malaria patients expressed CTLA4, compared to healthy controls (P<0.001), although the frequencies were much lower than for CD4+ T cells (6.5% versus 23%)." (PMID 27802341, 2016). "On the other hand, the identification of CD4+ and CD8+ epitopes from malaria is urgently required to track various vaccine approaches, mainly to evaluate candidates for compositions of subunit vaccines." (PMID 26858717, 2016). "In malaria, a variety immune cells are known to be activated such as CD8+ T, CD4+ T and NK cells, and their function can be regulated or impaired by Gal-9 in vitro." (PMID 27515948, 2016). "The results demonstrated a significant positive correlation between the CD4+/CD8+ T-cells (ratio) and plasmatic IL-10 levels (pg/mL) selectively in recurrent malaria patients." (PMID 27581163, 2016). "Furthermore, memory CD4 T cells from P. yoelii-infected mice were unable to respond ex vivo to S. Typhimurium Class II antigens flagellin, SseI and SseJ presented by naïve splenocytes, providing further evidence for a T cell-intrinsic defect in adaptive immunity during malaria." (PMID 26366739, 2015). "A limited number of studies have suggested that such CD4 T cell responses correlate with protection against infection in CHMI studies, and in children under natural malaria exposure." (PMID 26148007, 2015). "CD4+CD25hi+/CD4+CD25+ ratio, which represents Treg cell/effector T cell ratios, was found to be higher in both malaria and eBL patients than in controls." (PMID 28536409, 2015). "These highly reactive samples had CD4+ T cell counts greater than 500 cells/μL and low, to undetectable HIV viral loads, and is consistent with the observation that an increase in malaria prevalence in HIV is inversely correlated to CD4+ T cell count." (PMID 25928218, 2015). "The finding that both CD4+ and CD8+ T cells isolated from Plasmodium-infected humans produce IFN-γ is also observed in many mouse models of malaria." (PMID 26426121, 2015). "On the other hand, pre-patent filariasis exacerbates malaria severity through immunosuppression of IFN-γ and initiation of activation of CD4 + CD25 + FoxP3+ T-regulatory cells." (PMID 26377900, 2015). "Once an adaptive immune response is initiated, both CD4+ and CD8+ T cells become a major source of IFN-γ in response to both liver stage and blood stage malaria." (PMID 26426121, 2015). "A significant inverse correlation was observed between malaria-specific CD4+ T cell proliferation and cumulative prior incidence (Spearman's Rho = −0.39, P = 0.011), suggesting that heavy antigen exposure may result in a proliferative defect in malaria-specific CD4+ T cells." (PMID 24415936, 2014). "Previous studies using recombinant proteins or peptides based on PfEMP1 expressed on laboratory lines showed that individuals living in malaria-endemic areas harbored both IFN-γ− and IL-10–secreting Ag-specific CD4+ T cells." (PMID 24453249, 2014). "Thus, the absence of malaria-specific CD4+ T cells producing TNFα may be associated with the phenotype of asymptomatic infection." (PMID 24415936, 2014). "The identification of malaria responsive cell subsets is needed; the contribution of DCs, monocytes, CD4 or CD8 T cells, γδ T cells or NK cells to malaria antigen-specific responses and the influence of helminth infections on these subsets will be studied." (PMID 25120947, 2014). "The combined blockade of PD-L1 and LAG-3 increased numbers of CD4+ TFH and GC B cells along with higher antibody titers which contributed to better control of blood stage of malaria." (PMID 24904561, 2014). "Together these data indicate that the functional phenotype of the malaria-specific T cell response is heavily influenced by malaria exposure intensity, with IFNγ/IL10 co-producing CD4+ T cells dominating this response among highly exposed children." (PMID 24415936, 2014).